TAFA4 (TAFA chemokine like family member 4)
Description:
Modulates injury-induced and chemical pain hypersensitivity (By similarity). Ligand of FPR1, can chemoattract macrophages, promote phagocytosis and increase ROS release.
Synonyms: FAM19A4; TAFA-4
Tractability: Antibody: UniProt places it where antibodies can reach, with high confidence; UniProt predicts a signal peptide or a membrane-spanning region; its Gene Ontology location is reachable by antibodies, with medium confidence.
Gene: Protein-coding gene on chromosome 3 (68,731,764 to 68,953,297, reverse strand). Ensembl gene ENSG00000163377.
Subcellular location: Secreted
Gene Ontology:
Molecular function: protein binding; receptor ligand activity
Biological process: macrophage chemotaxis; phagocytosis; regulation of signaling receptor activity; superoxide anion generation; signal transduction
Cellular component: extracellular region; glutamatergic synapse; synaptic vesicle membrane
Genetic constraint (gnomAD): Loss-of-function variants: 19 observed, 20.9 expected, observed/expected ratio (o/e) 0.91, 90% interval 0.63 to 1.33. The upper end of that interval is the gene's LOEUF score, 1.33, which puts it in group 5 of 6, group 1 being the genes least tolerant of losing a copy. Missense variants: 207 observed, 186.95 expected, observed/expected ratio (o/e) 1.11, 90% interval 0.99 to 1.24. Synonymous variants: 70 observed, 70.02 expected, observed/expected ratio (o/e) 1, 90% interval 0.82 to 1.22.
Homologues: Orthologues: macaque TAFA4 (99% identical), chimpanzee TAFA4 (98% identical), pig TAFA4 (97% identical), dog TAFA4 (95% identical), guinea pig TAFA4 (94% identical), rabbit TAFA4 (92% identical), rat Tafa4 (91% identical), mouse Tafa4 (90% identical), tropical clawed frog tafa4 (84% identical), zebrafish tafa4a (58% identical). Paralogues in human: TAFA2 (61% identical), TAFA3 (59% identical), TAFA1 (54% identical).
Diseases named in the same sentence as TAFA4 in open-access papers:
TAFA4 is named in the same sentence as 24 diseases in open-access papers, as found by Europe PMC text mining. Sharing a sentence is not in itself a finding about the gene and the disease. The quoted sentences say what the papers report.
cervical carcinoma (12 papers, 2018 to 2025). A carcinoma arising from either the exocervical squamous epithelium or the endocervical glandular epithelium. "Among TAFA ligands, TAFA4, also called FAM19A4 is a secreted chemokine-like protein of 12 kDa weight, which has been relatively well studied, with research implicating its importance for the detection of cervical cancer." (PMID 35712659, 2022).
allergic rhinitis (1 paper, 2022). Inflammation of the nasal mucous membranes caused by an IgE-mediated response to external allergens. "The objective of this study is to promote the efficacy of AIT in experimental allergic rhinitis (AR) by the concurrent use of TAFA chemokine as a family member 4 (TAFA4)." (PMID 36316414, 2022).
cancer (10 papers, 2018 to 2025). A tumor composed of atypical neoplastic, often pleomorphic cells that invade other tissues. "Further studies are required to confirm the involvement of DNA methylation of TAFA4/FAM19A4 in the development of cancers in the cervix and lung, and to add DNA methylation of TAFA4/FAM19A4 as an additional diagnostic marker to improve specificity and sensitivity." (PMID 35712659, 2022). "The critical role of TAFA4 in cancer diagnosis continues to be a vital area of research." (PMID 35712659, 2022).
infection (2 papers, 2020 to 2022). The state of being infected such as from the introduction of a foreign agent such as serum, vaccine, antigenic substance or organism. "Previous research has identified TAFA4 as a cytokine ligand of FPR1 for the inflammatory response to pathogenic infections." (PMID 35712659, 2022). "TAFA4 therefore appears to play a critical role in the chemoattraction and phagocytosis of macrophages, and ROS release following an infection." (PMID 35712659, 2022).
TAFA4 also shares sentences with these, for which no sentence is quoted: tumor (3 papers); asthma (2); bladder cancer (2); cervical dysplasia (2); cervical squamous cell carcinoma (2); squamous intraepithelial lesions (2); adenocarcinoma (1); adenocarcinoma in situ (1); airway allergy (1); colitis (1); endocervical adenocarcinoma (1); injury (1); lung carcinoma (1); lymph node metastasis (1); oral cancers (1); prostate carcinoma (1); prostate tumors (1); Sciatica (1); squamous cell carcinoma (1); viral infection (1).